VAV1 (vav guanine nucleotide exchange factor 1)
Diseases named in the same sentence as VAV1 in open-access papers (continued):
Sharing a sentence is not in itself a finding about the gene and the disease.
tumor (57 papers, 2008 to 2025). "One of them is that the oncogenic driver activity of the Vav1 gain‐of‐function mutations is highly specific for specific tumours (AITL) and cell types (TFH cells)." (PMID 35895495, 2022). "Immunohistochemical analysis of Vav1 and CSF-1 expression of primary human lung tumors pointed to a strong link between these proteins, associated with to tumor grade." (PMID 35326399, 2022). "This mouse model will be also useful to study the influence of oncogenic VAV1 signalling on other tumour types and the type of cooperating mutations that are required to trigger tumour formation or progression." (PMID 35895495, 2022). "Taking together, the upregulation of VAV2 catalytic activity facilitates tumor development, similar to the effect caused by some VAV1 mutations in PTCLs." (PMID 34571765, 2021). "Conversely, VAV1 may function as a tumor suppressor in immature T cells, with its loss leading to acute lymphoblastic leukemia in T cells." (PMID 39200159, 2024). "To assess the spectrum of tumours induced by the expression of VAV1 gain‐of‐function mutations in cancer development, we used the CRISPR‐Cas9 gene editing technique to generate mice bearing a Vav1 mutant allele encoding a CSH3‐truncated protein (amino acids 835–845, referred to hereafter as VAV1ΔC)." (PMID 35895495, 2022). "Indeed, the discovery of potential gain-of-function VAV1 mutations in specific tumor subtypes reinforced this functional archetype." (PMID 34571765, 2021). "Discerning the functional significance of these alterations in the context of VAV1 mutations, and in particular those that disrupt the tumor suppressor activity, could provide further insight into the exacerbated signaling that occurs in PTCLs." (PMID 34571765, 2021). "Moreover, VAV1 was significantly associated with GS, pathological T staging, lymph node invasion (pathological N staging), and nerve invasion at the protein level, indicating its effect on tumor cell invasiveness." (PMID 34804963, 2021). "Separately, both GLI1 and VAV1 have been shown to be required for PDAC tumor cell proliferation, and the presence of either protein in PDAC has been associated with poor prognosis." (PMID 41314543, 2025). "We further combined IL-2 with PD-1 blocking antibody for tumor immunotherapy in March5+/f and March5+/f: Vav1-Cre mice." (PMID 37932447, 2023). "We isolated tumor-infiltrating lymphocytes (TILs) from the tumor tissues of March5+/f and March5+/f:Vav1-Cre mice and analyzed the immunological changes in tumors." (PMID 37932447, 2023). "The results showed that the anti-tumor effects of combined IL-2 with PD-1 blockade in March5+/f:Vav1-Cre mice were superior to that in March5+/f mice, which eliminated tumors in 2 out of 8 March5+/f:Vav1-Cre mice." (PMID 37932447, 2023). "Administration of IL-2 in March5+/f:Vav1-Cre mice showed increased efficacy in suppression of tumor growth and improvement of the overall survival comparing to that in March5+/f mice." (PMID 37932447, 2023). "Most of the studies that reported an overexpression of VAV1 in human cancer also pointed to the correlation between VAV1 expression and tumor severity." (PMID 37174676, 2023). "In most of these cases, VAV1, which is usually expressed in the cytoplasm, was localized to the nuclei of tumor cells." (PMID 37174676, 2023). "VAV1 can also influence the tumor microenvironment in an autocrine/paracrine manner, potentially leading to tumor growth." (PMID 37174676, 2023). "Yet, it is obvious that Vav1’s ectopic expression impacts tumor development either in the pancreas when it is co-expressed with mutant K-Ras or when it is expressed in various tissues under the Rosa promoter." (PMID 35326399, 2022).
tumor (continued). "The elimination of this VAV1‐regulated tumour suppressor pathway is critical for the fitness of T cell acute lymphoblastic leukaemia of the TLX+ clinical subtype." (PMID 35895495, 2022). "It was indicated that VAV1 expression was higher in normal tissues than in tumor samples, whereas, the elevated expression of RHOA and ZC3HAV1 was observed in the tumor group." (PMID 36224658, 2022). "Vav1’s overexpression in epithelial tissues where it leads to tumor generation was thus far attributed to its promoter methylation status." (PMID 35326399, 2022). "To understand their pathogenic potential, we generated a gene‐edited mouse model that expresses a VAV1 mutant protein that recapitulates the signalling alterations present in the VAV1 mutant subclass most frequently found in tumours." (PMID 35895495, 2022). "Vav1 is a well-known signal transducer that can affect tumor microenvironment through its involvement in numerous signaling pathways." (PMID 35326399, 2022). "Despite the progress made in the understanding of the role of VAV proteins in cancer, the recent discovery of the tumor suppressor role of VAV1 has further highlighted the need to study the function of these proteins beyond their catalytic activity." (PMID 34571765, 2021). "Among the proteins up-regulated by ATRA, Vav1 is involved in maturation and function of haematopoietic cells and is essential for retinoids induced differentiation of tumor promyelocytes." (PMID 33165749, 2021). "Conversely, tumor cell membrane-bound MIC (mMIC) stimulates NK cell cytotoxicity through activating PLC2γ2/SLP-76/Vav1 pathway." (PMID 34294876, 2021). "For certain genes (Il10, Csf3, Cxcl1, Ccl2, Gata3, Il5, and Il13), there was a clear difference between the EC and HC Shb KO effects using Cdh5-CreERt2 or Vav1-Cre tumor-bearing mice, indicating that these effects reflect EC cell autonomy of Shb gene deletion." (PMID 34768912, 2021). "Our results show that NCFs and their coexpressed genes, including SPI1, HCK, VAV1, CD53, and ITGB2, are significantly associated with tumor-infiltrating immune cells, especially with immunosuppressive macrophages." (PMID 34708124, 2021). "In line with this, the discovery of the catalysis-independent tumor suppressor function of VAV1 buffering NOTCH1 signaling in T cells further hindered the understanding of the role of VAV proteins in cancer." (PMID 34571765, 2021). "When Vav1 was the only gene expressed, it did not lead to the development of any malignant lesions in the pancreas, suggesting that Vav1 can influence tumor development only when it functions together with other signaling proteins, such as K-RasG12D." (PMID 32277014, 2020). "By using pancreatic cell lines expressing different basal levels of Vav1, we demonstrated here that Vav1 down-regulates the expression of Akt2, known to correlate with tumor metastases and resistance to therapy." (PMID 32993067, 2020). "In the current study of the role of Vav1 in tumor development, our novel transgenic K-RasG12D/Vav1 mouse model was used for the first time." (PMID 32277014, 2020). "Among these, SMAD-dependent cellular responses of the TGFβ signaling pathway have been reported to activate ectopic VAV1 expression via hypomethylation of the VAV1 promoter and regulate tumor progression." (PMID 32552862, 2020). "Gene Hsa.44676 (VAV1) promotes cancer growth by instigating tumor-microenvironment cross-talk via growth factor secretion." (PMID 31150453, 2019). "More importantly, Vav1 levels are also lower in tumor cells from a TLX1+ T-ALL patient than in two TLX– T-ALL patient-derived samples." (PMID 29136506, 2017). "Taken together, these results indicate that Vav1 acts as a tumor-suppressor gene at the DN1-DN2 and ISP T cell developmental stages." (PMID 29136506, 2017). "The investigation of this rather paradoxical effect led us to discover a Vav1-dependent tumor-suppressor pathway involved in ICN1 regulation in immature T cells." (PMID 29136506, 2017).
tumor (continued). "and X.R.B., unpublished data), suggesting that the Vav1 tumor-suppressor and protumorigenic activities can become deregulated independently or concurrently in a tumor- and patient-specific manner." (PMID 29136506, 2017). "Contrary to this paradigm, we demonstrate here that Vav1 can perform tumor-suppressor functions in immature T cells." (PMID 29136506, 2017). "No statistically significant changes in the amount of ICN1 and ICN1 downstream gene targets are detected in tumor T cells from DMBA-treated WT mice, indicating that the deregulation of this cascade is intrinsic to the Vav1 deficiency." (PMID 29136506, 2017). "Vav1−/− tumor cells exhibit large transcriptional changes that involve the deregulation of “common”, DN-specific, and CD8+-specific gene sets." (PMID 29136506, 2017). "We report here that the GEF Vav1 unexpectedly possesses tumor-suppressor functions in immature T cells." (PMID 29136506, 2017). "The overall weight of the tumours generated by onco-Vav and D797N-expressing cells was highly above those generated by wt-Vav1 or empty vector when present." (PMID 25426554, 2015). "Vav1 was also identified in more than 50% of 95 pancreatic ductal adenocarcinoma (PDA) tumor specimens examined." (PMID 26353933, 2015). "The human origin of these tumor masses was confirmed by the immunohistochemical analysis of the human Cytokeratin and Vav1." (PMID 24962430, 2014). "The relationships among the amounts of Vav1 inside the nuclear compartment of tumor cells and tumor size, histotype, tumor grade, proliferation index and receptors status were not statistically significant." (PMID 24962430, 2014). "This in contrast with the whole cellular level of Vav1 that, in a study less extensive and including a great variety of tumor stages, was reported to be positively correlated with the expression of ER and PR." (PMID 24962430, 2014). "In fact, only in ER+ tumors, high amounts of Vav1 inside the nucleus of tumor cells correlate with the post-menopausal status." (PMID 24962430, 2014). "Recent studies revealed that wild-type Vav1, which is normally tightly restricted to hematopoietic cells, is expressed in several human tumor malignancies, suggesting that it has a role in human cancer." (PMID 23342133, 2013). "Flow cytometry analysis of cells obtained from the thymus, spleen and bone marrow of tumor–bearing Vav1–/–;Rasgrf2–/– and Vav1–/– animals revealed the presence of a new population characterized by the surface expression of CD3, a T–cell specific marker." (PMID 20011522, 2009). "Tumour tissue exhibited high levels of all three Rho activators Trio, Vav1 and TIAM-1 compared with normal background breast tissue, reaching a level of significance for the GEF Trio (p = 0.013)." (PMID 18925966, 2008). "In addition, VAV1 is involved in regulating cell migration and invasion, properties that are critical for tumor cell metastasis." (PMID 37174676, 2023). "In these models, March5+/f:Vav1-Cre mice showed slower tumor progression than March5+/f mice." (PMID 37932447, 2023). "We demonstrated here the ability of the Vav1-induced miR-29b to down-regulate Akt2 in MDA-MB-231 cells both in vitro and in tumor xenografts derived from MDA-MB-231 cells stably over-expressing Vav1, ascertaining the existence of a Vav1/miR-29b/Akt2 axis in these TNBC cells." (PMID 35743776, 2022). "VAV1‐mutant tumor cells, like the mPTCL and clinical PTCL, co‐expressed Th2 and Tfh markers." (PMID 35510955, 2022). "Our findings provide a novel mechanism by which Vav1 contributes to tumor propagation." (PMID 35326399, 2022). "In any case, all these data suggest that the inhibition of VAV1 could represent a potential therapeutic avenue to treat specific tumor types." (PMID 35895495, 2022). "Thus, a variety of loss‐of‐function studies using cells or mouse models have demonstrated that the elimination of wild‐type VAV1 can impair the formation of specific tumor types." (PMID 35895495, 2022).
tumor (continued). "To find out whether this is a general phenomenon, we expressed Vav1 under a ubiquitous promoter, Rosa26, and followed tumor generation." (PMID 35326399, 2022). "During the development of a host of tumor diseases, Vav1 promotes cell proliferation and invasion." (PMID 33995034, 2021). "Contrary to this paradigm, we demonstrated that VAV1 could unexpectedly act as a tumor suppressor in some in vivo contexts." (PMID 34571765, 2021). "An important issue to be further addressed in the near future is to verify the relevance of the VAV1-dependent tumor suppressor function in VAV2- and VAV3-driven tumors, particularly in those that may be NOTCH1-dependent." (PMID 34571765, 2021). "Moreover, these proteins can directly repress the VAV1 gene, resulting in a downmodulation of the tumor suppressor role of the protein." (PMID 34571765, 2021). "To determine whether disruption of Kdm6a in HSPCs only (mediated by Vav1-Cre) might lead to hematopoietic malignancies, we performed an 18-month tumor watch." (PMID 34780480, 2021). "Finally, we can conclude that Vav1 is unable to induce the maturation of β-cells but is an essential molecule in the differentiation process of both normal and tumor precursors activated by ATRA." (PMID 33165749, 2021). "Vav1 knockdown reduced tumor growth in nude mice from NSCLC cells expressing oncogenic K-Ras." (PMID 32322580, 2020). "Taking into consideration our genetic and signaling results, we surmised that the Vav1-Cbl-b axis could play tumor-suppressor roles in human T-ALL, namely those of the immature, TCR– phenotype." (PMID 29136506, 2017). "Vav1 overexpression increases tumor cell survival, proliferation, and metastasis, thus drugs that targeted degradation Vav1 may be potent inhibitors of tumor cell migration." (PMID 28881704, 2017). "Buttressing this hypothesis, the “common” Vav1−/− tumor gene signature is also similar to the transcriptome of T-ALL cells generated upon ectopic expression of ICN1 in mouse bone marrow precursors." (PMID 29136506, 2017). "Thus, we have shown that Vav1 can play a GTPase-independent, tumor-suppressor-like role that mediates Notch1 signaling in T cells." (PMID 29136506, 2017). "Interestingly, Vav1 proteins extracted from the tumour cells exhibited activated pY174 at levels comparable to those observed in injected cells reflecting Vav1 activation." (PMID 25426554, 2015). "Additionally, our results strengthen the importance of activating single point mutations in the C-SH3 domain that abrogate Vav1 autoinhibition, potentiate the GEF activity and consequently facilitate tumour progression." (PMID 25426554, 2015). "However, D797N-derived tumours showed a more heterogeneous size than did onco-Vav while wt-Vav1 expressing cells only generated small nodes." (PMID 25426554, 2015). "Our finding that Vav1 affects CSF1 expression and secretion and that the tumor microenvironment might also be involved in such a process prompted us to ask whether CSF1 is critical for Vav1 dependent lung tumor growth in vitro." (PMID 25313137, 2014). "Interestingly, this influence of Vav1 expression was observed even in the presence of mutant K-Ras, demonstrating the critical role of Vav1 in tumor development." (PMID 25313137, 2014). "Finally, immunohistochemical analysis of primary human lung tumors revealed a positive correlation between Vav1 and CSF1 expression, which was associated with tumor grade." (PMID 25313137, 2014). "Variation in the expression levels of the VAV1 mRNA between normal and tumor cells." (PMID 20011522, 2009). "However, if in the future it is proposed to use azathioprine to treat VAV1-positive cancer, it would be useful to determine whether VAV1 in the tumor leads to the activation of the RAC1 pathway before treatment." (PMID 37174676, 2023). "Thus, Vav1 could influence tumor growth and the tumor’s microenvironment via CSF-1 in an autocrine/paracrine mechanism." (PMID 35326399, 2022).
tumor (continued). "Our laboratory was the first to analyze whether wild-type Vav1 leads to tumor generation in vivo." (PMID 35326399, 2022). "At variance with hematopoietic cells, in which Vav1 plays a well-known role in maturation and function, nothing is still known about its possible involvement in differentiation of solid tissues, in which its presence has been mainly correlated with the appearance of a tumor phenotype." (PMID 33165749, 2021). "Previous studies have shown that VAV1 could promote T cell transformation into Tregs, while Tregs could also indirectly induce macrophage VAV1 which enhances the efferocytosis of macrophages, leading to tumor immune escape." (PMID 34804963, 2021). "Aberrant expression of Vav1 in non-hematopoietic cells was almost always associated with the appearance of a tumor phenotype and, with the exception of breast tumors, with a negative tumor prognosis." (PMID 33165749, 2021). "Despite this relevant difference, VAV proteins share a very similar structure and can exhibit overlapping functions, suggesting that VAV2 and VAV3 might play tumor suppressor roles similar to those carried out by VAV1 beyond the long-held signaling archetype for RHO GEFs." (PMID 34571765, 2021). "However, studies have detected Vav1 expression in several types of cancer cells and tumor tissue, including neuroblastoma, ovarian, lung, pancreatic, head and neck, gastric, endometrial, cervical, and colorectal cancer, metastatic melanoma, and B-cell chronic lymphocytic leukemia." (PMID 32322580, 2020). "Also in tumor tissues, we found that high levels of Vav1 and low levels of p‐Akt correlated with low Cyclin D1 staining, suggestive of the inverse relationship between Vav1 and activated Akt1." (PMID 29658179, 2018). "Interestingly, the expression of VAV1 mutants or wild-type VAV1 did not give rise to tumors, even after long periods of time since onset; yet, whether there are VAV1 mutants that could lead to tumor generation when expressed alone in GEMMs remains to be tested." (PMID 37174676, 2023). "Nonetheless, the expression of VAV1, RHOA, and ZC3HAV1 in the tumor group was all up-regulated than that in the normal group in several HCC cohorts from Oncomine database." (PMID 36224658, 2022). "After that, We investigated the difference in transcriptional expression of VAV1, RHOA, and ZC3HAV1 between tumor samples and adjacent normal liver tissues in various HCC datasets from TCGA, ICGC, and GEO14520." (PMID 36224658, 2022). "Our results revealed an unprecedented role of Vav1 in sustaining the ATRA mediated differentiation of normal and tumor cells to insulin producing cells." (PMID 33165749, 2021). "Our study found that VAV1 was a key link connecting Tregs and five immune-relevant KEGG pathways and revealed the features of tumor invasion and immunosuppression." (PMID 34804963, 2021). "We found that CD155/PVR-CD226 signaling occurs through VAV1 phosphorylation and BCL9 inhibition promotes antibody-mediated PD-1 blockade via promoting cytotoxic CD8+ T cell tumor infiltration in mouse models." (PMID 34417435, 2021). "To further confirm the requirement of Hippo kinases for RASSF2-mediated tumor suppression we generated mice with conditional gene inactivation of both MST1 (Stk4) and MST2 (Stk3) in hematopoietic cells (Vav1-Cre)." (PMID 32029705, 2020). "PIK3R1 and VAV1 are known oncogenes, SYK is a tumor suppressor gene, and PTPN6 has a tumor suppressor role." (PMID 32293263, 2020). "Cells expressing the E59K and D517E Vav1 mutants resulted in markedly increased tumor sizes compared to tumors generated by NIH3T3 cells expressing pcDNA3, Vav1, or L801P." (PMID 30297765, 2018). "Consistent up-regulation of VAV1 and VAV2 observed across all tumours, was also replicated in a previous report." (PMID 28886030, 2017).